MIR1244-4 (microRNA 1244-4)
Synonyms: hsa-mir-1244-4
Gene: MicroRNA gene on chromosome 12 (12,111,952 to 12,112,036, forward strand). Ensembl gene ENSG00000283475.
Homologues: Paralogues in human: MIR1244-1 (100% identical), MIR1244-2 (100% identical), MIR1244-3 (100% identical).